CXCL1 (C-X-C motif chemokine ligand 1)
Diseases named in the same sentence as CXCL1 in open-access papers (continued):
Sharing a sentence is not in itself a finding about the gene and the disease.
glioma (29 papers, 2009 to 2025). A benign or malignant brain and spinal cord tumor that arises from glial cells (astrocytes, oligodendrocytes, ependymal cells). "CXCL1 has previously been implicated in promoting angiogenesis and oncogenesis in various cancer types, including gliomas." (PMID 19558675, 2009). "IL-7, IL-8, and GRO/CXCL1 have each been implicated in glioma biology." (PMID 30379898, 2018). "Also, elevated levels of CXCL1 are associated with a worse prognosis for glioma patients." (PMID 38673949, 2024). "However, the role of CXCL1 in the proliferation of glioma cells and its underlying mechanism remain unclear." (PMID 37594930, 2023). "Blocking CXCL1/2 dramatically prolongs overall survival in mice treated with temozolomide, suggesting that these chemokines regulate tumor resistance during glioma treatment." (PMID 40297580, 2025). "Umap plots indicated that CXCL1 is relatively high expressed in the malignant cell populations within gliomas." (PMID 40636690, 2025). "Increased CXCL1 expression was closely related to immunosuppressive characteristics in gliomas, possibly via remodeling the TIME composition by recruiting CXCR2+ inflammatory immune cells." (PMID 38342629, 2024). "The genes of the next chemokines, CXCL1,-2,-3,-5,-6,-8, have a very similar expression pattern, which includes a very restricted subpopulation of glioma cells, pericytes, and myeloid cells (among the latter, CXCL2,-3,-8 are highly expressed)." (PMID 39272976, 2024). "The exception was brain lower-grade glioma, where higher CXCL1 expression correlated with worse prognosis, while CXCL2 and CXCL5 expression correlated with better outcomes." (PMID 37686093, 2023). "To further verify the effect of CXCL1 on the proliferation of C6 glioma cells, we constructed an interfering RNA (RNAi) lentiviral vector targeting the rat CXCL1 gene." (PMID 37594930, 2023). "And exogenous glial cell line-derived neurotrophic factor (GDNF) induced proliferation and up-regulated the level of CXCL1 in rat C6 glioma cells determined by sqPCR and ELISA." (PMID 37594930, 2023). "In this study, we found CXCL1 was a proliferation-related gene by RNA-seq together with bioinformatics technology, and exogenous GDNF up-regulated the level of CXCL1 in rat C6 glioma cells determined by sqPCR and ELISA." (PMID 37594930, 2023). "To further validate the effect of CXCL1 on the proliferation of C6 glioma cells, we constructed a lentiviral vector with an interfering RNA (RNAi) targeting the rat CXCL1 gene and which was used to infect C6 cells." (PMID 37594930, 2023). "Present studies show that CXCL1 acts as a carcinogen in glioma which promotes the proliferation and migration of glioma cells." (PMID 37594930, 2023). "For example, the overexpression of CXCL1 had been demonstrated as a poor prognostic indicator and induced radio‐resistance via NF‐κB signaling in glioma patients." (PMID 35985661, 2022). "Co-culture of mast cells with glioma cells induces the expression of serglycin, CD44, ZEB1, vimentin, CXCL10, CXCL12, and TNF-α in glioma cells and IL-6 and CXCL1 in mast cells, creating an inflammatory milieu that induce glioma cell aggressiveness." (PMID 35494005, 2022). "A 44-plex cytokine array (Luminex) revealed glial cells are a major source of pro-tumorigenic CCL2 while glioma cells express CXCL1 and CXCL8." (PMID 35906273, 2022). "In the previous study, it had been demonstrated that CXCL1 played a poor prognostic indicator and induced radio‐resistance via NF‐κB signaling in glioma patients." (PMID 35985661, 2022). "Meanwhile, IL‐6 and CXCL1 were obviously increased in the course of glioma radiotherapy, and the inflammatory activity was obviously enhanced by transcriptome analysis of radiotherapy resistance." (PMID 34216174, 2021). "At present, radiotherapy plays an important role in the treatment of glioma, but significantly increases CXCL1, IL‐6 and IL‐8 amounts." (PMID 34216174, 2021).
glioma (continued). "Targeting CXCL1/2 with standard chemotherapy can improve the chemotherapy efficiency of glioma and prolong the survival of glioma mice." (PMID 34630121, 2021). "In the training cohort, CXCL14 (P value < 0.001), CXCL9 (P value < 0.05), CXCL10 (P value < 0.001), CXCL11 (P value < 0.001), CXCL6 (P value < 0.001), and CXCL1 (P value < 0.001) were enriched in the IDH wide-type gliomas." (PMID 34603309, 2021). "Pro‐inflammatory factors have been described in glioma, and it is generally considered that IL‐6, IL‐8, CXCL1, CXCL10 and TGFβ2 are pro‐tumour cytokines closely related to glioma progression." (PMID 34216174, 2021). "GRO/CXCL1 levels were higher in gliomas compared to autoimmune/DM (p = 0.0044), lymphomas (p = 0.0476) and controls (p = 0.0167)." (PMID 30379898, 2018). "Gliomas can also be distinguished from autoimmune/demyelinating disorders by higher levels of GRO/CXCL1 (p = 0.0044), IL-7 (p = 0.0035) and IL-8 (p = 0.0176)." (PMID 30379898, 2018). "We identified several targets involved in glioma growth and migration, specifically CXCL1, CD81, TPT1, Gas6 and AXL proteins." (PMID 19558675, 2009). "Moreover, temozolomide treatment of glioma significantly induces the expression of CXCL1 and CXCL2, chemokines that promote the migration of bone marrow-derived inhibitory cells to tumors." (PMID 40297580, 2025). "In glioblastoma tumors, CXCL1 expression is higher than in low-grade gliomas." (PMID 38673949, 2024). "To evaluate the combined impact of the developing glioma and SorLA loss from host cells on the tumor microenvironment, we first assayed the levels of selected cytokines (TNFα, MIP2, CCL5, CXCL1, IL1β, IL2, IL6, and IL10) in the tissue lysates derived from tumor-bearing and tumor-free hemispheres." (PMID 38499808, 2024). "IL‐6, CXCL1 and TGFβ2 play an important role in glioma radiotherapy resistance." (PMID 34216174, 2021). "At present, radiotherapy is one of the main methods to treat glioma, but it leads to an obvious increase in inflammatory factors in the tumour microenvironment, especially IL‐6 and CXCL1, which plays a role in tumour to resistance radiotherapy and tumorigenesis." (PMID 34216174, 2021). "The results indicated that CXCL1 was markedly overexpressed in GBM compared with low‐grade glioma." (PMID 32187449, 2020). "Next, elevated CXCL1 expression was closely related to poor prognosis in glioma/GBM patients." (PMID 32187449, 2020). "We also observed an increase in IL-6 and CXCL1 expression in MCs co-cultured with glioma cells." (PMID 28445977, 2017). "In addition, the production of CXCL1 has also been shown to be upregulated in glioma tissues where it mediates the proliferation of glial progenitor cells during neurodevelopment and contributes to glioma formation." (PMID 37594930, 2023). "ChIP-seq and qPCR demonstrated that reduced crotonylation suppressed CXCL1 expression and promoted GZMB expression in the glioma microenvironment." (PMID 40636690, 2025). "Together, these data suggested that Fn promoted glioma growth by increasing the levels of N-acetylneuraminic acid and the expression of CCL2, CXCL1, and CXCL2." (PMID 39660865, 2025). "We will further explore the specific mechanisms by which Fn upregulates cytokines such as CCL2, CXCL1, and CXCL2 to promote glioma development in future studies." (PMID 39660865, 2025). "We found Fn promotes glioma proliferation and upregulates CCL2, CXCL1, and CXCL2 levels in vivo and in vitro models of glioma." (PMID 39660865, 2025). "Neutrophils are recruited to glioma inflammatory regions by chemokines such as CXCL1, CXCL2, CXCL3, CXCL5, CXCL6, IL-8 (CXCL8), and IL-1β, which are secreted by glioma cells." (PMID 41272822, 2025). "Both in vivo and in vitro experiments demonstrated that Fn, as a key bacterium enriched in glioma tissue, promotes glioma proliferation and increases the expression of CCL2, CXCL1, and CXCL2." (PMID 39660865, 2025).
glioma (continued). "In this study, we explored the relationship between GDNF, NF-κB, CXCL1, and cell proliferation and proved that GDNF promoted C6 glioma cell proliferation through the NF-κB/CXCL1 signaling pathway." (PMID 37594930, 2023). "The expression of COX-2 in glioma cells promoted the anabolic metabolism of PGE2, up-regulating the expression of IL-1β and CXCL1 to recruit neutrophils." (PMID 34211978, 2021). "U87 glioma cells express several chemokines (CCL2, CCL20, CXCL1, CXCL2, CXCL8, etc.), among which IL-8 is the most abundant after radiation." (PMID 31488817, 2019). "IL-7, IL-8, GRO/CXCL1 and VEGF were informative in distinguishing WHO grade III and IV gliomas from the other disease states studied." (PMID 30379898, 2018). "In glioma, MDK secreted by GBM cells drives macrophage polarization toward the M2 phenotype by activating receptors on macrophages, leading to the secretion of cytokines such as CXCL1 and thereby fostering an immunosuppressive environment." (PMID 41246334, 2025). "In addition, both in vivo and in vitro models of glioma show that Fusobacterium nucleatum promotes glioma proliferation and upregulates CCL2, CXCL1, and CXCL2 levels." (PMID 39660865, 2025). "We identified an increase in CXCL1, CXCL8, and CCL2 upon combining glioma cells with glial cells." (PMID 35906273, 2022). "Additionally, of the non-infectious diseases, gliomas can be distinguished from lymphomas by higher levels of GRO/CXCL1 (p = 0.0476), IL-7 (p = 0.0119), and IL-8 (p = 0.0460)." (PMID 30379898, 2018). "The level of CXCL1 expression in gliomas may not be highest in glioblastoma." (PMID 38673949, 2024). "In addition to suppressing immunity, CXCL1 and CXCL2 also recruit myeloid cells to produce paracrine factors such as S100A9 and promote tumor cell survival found that silencing CXCL1 can down-regulate NF-κB and mesenchymal cell transformation, and inhibit the growth of human glioma xenograft." (PMID 34630121, 2021). "The results showed that there were trends linking these cytokines, CCL20, CXCL1, CXCL2, CXCL5, and CXCL16, to ADO expression in gliomas but these correlations were not significant, probably due to the low number of patients recruited to the study." (PMID 33483477, 2021). "The original RNA-seq results suggested that glioma patients have higher levels of CCL20, CXCL1, CXCL2, CXCL5, and CXCL16 compared to noncancerous patients and that the levels of these small chemotactic cytokines in glioma are correlated with malignancy." (PMID 33483477, 2021).
influenza (29 papers, 2010 to 2025). An acute viral infection of the respiratory tract, occurring in isolated cases, in epidemics, or in pandemics; it is caused by serologically different strains of viruses (influenzaviruses) designated A, B, and C, has a 3-day incubation period, and usually lasts for 3 to 10 days. "In influenza infection, Setdb2 did the same at the Cxcl1 gene, reducing neutrophil-driven inflammation." (PMID 40948770, 2025). "In a different model of A. fumigatus superinfection following IAV infection, mice infected with influenza infection had decreased pulmonary concentrations of the neutrophil chemoattractants CXCL1 and CXCL2 following A. fumigatus challenge." (PMID 37681974, 2023). "In influenza–bacterial coinfection, this results in reduced CXCL1 secretion, less neutrophil recruitment, and reduced bacterial control, thus identifying a molecular pathway leading from influenza-induced IFN-αβ to facilitated bacterial invasion." (PMID 25714109, 2015). "The chemokine KC/CXCL1 plays a critical role in preventing bacterial pneumonia after influenza infection." (PMID 22792270, 2012). "It has been previously reported that blocking expression of CXCR2, the receptor for CXCL1, resulted in a reduction of neutrophil influx with prolonged host survival during influenza infection." (PMID 22072963, 2011). "As one of the natural ligands of CCR5, CCL5/CCR5 can mediate the recruitment and activation of neutrophils and monocytes during influenza, and CXCL1 can chemotactic T cells, monocytes, neutrophils and other immune cells when combined with its specific CXCR2 receptor." (PMID 37957672, 2023). "However, all experimental studies of the importance of CXCL1 in influenza are based on mouse studies." (PMID 36613652, 2022). "Additionally, we noted that increased IFN-β correlated with increased CCL2, CXCL1 and nitric oxide synthase (NOS2) expression in the lungs, which has been associated with severe influenza infections." (PMID 34691044, 2021). "Furthermore, activation of PAR-1 triggers IL-6 and CXCL1/KC release and increases lung inflammation in mice after influenza infection." (PMID 34658893, 2021). "In contrast to the findings obtained with the bacterial infection model, those obtained with the influenza-infected CXCL5-/- mice indicated that the levels of the major neutrophil chemoattractants CXCL1 and CXCL2 in the lungs were significantly decreased during the early infection stage." (PMID 34868067, 2021). "CXCL1 may play a significant role in the course of influenza." (PMID 36613652, 2022). "Considering abundant expression of CXCL5 in the infected lung during early influenza infection stage, CXCL5 deficiency might down-regulate CXCR2 axis in lung epithelial cells and lead to reduced CXCL1/2 expression form the cells which in turn decreasing neutrophil infiltration." (PMID 34868067, 2021). "Influenza infected NOX4 TG mice had decreased expression of CXCL10, CCL3, CXCL1 and CXCL2 three days post infection." (PMID 35601109, 2022). "Previous research has shown that inflammation-related factors (IL-1, TNF, CXCL1, CXCL2, S100A8, and S100A9) predominantly express in neutrophils, and neutrophils infiltration largely account for lethal influenza infection." (PMID 35495713, 2022). "Expression of the main neutrophil chemoattractants CXCL1, CXCL2, and CXCL5 were induced upon influenza infection, but were unaffected by IL-1β." (PMID 24918427, 2014). "The concentrations of the cytokines IL-1β, IL-6, TNF-α, CXCL1,CXCL2, CCL5, IFN-γ and IL-12p40 were evaluated in lung homogenates ofcontrol and Influenza infected mice." (PMID 21079759, 2010). "Furthermore, the levels of CXCL13 in the culture supernatants of influenza-infected macrophages were significantly decreased upon the addition of recombinant CXCL5, recombinant CXCL1 and CXCL2, or all the proteins combined." (PMID 34868067, 2021).
influenza (continued). "Similarly, CCL2 (Ccl2), a ligand for CCR2 that recruits CCR2+ inflammatory monocytes, as well as CXCL1 (Cxcl1), CXCL2 (Cxcl2), and CXCL5 (Cxcl5), which are ligands of CXCR2 that induce neutrophil infiltration in influenza-infected lungs, showed notable decreases in NOD.SCID mice." (PMID 37904257, 2023). "CXCL1 and CXCL2 expression was also induced in influenza-infected AMs; however, CXCL5 expression was not induced based on the detection of both mRNA and protein levels." (PMID 34868067, 2021). "Similarly, whereas BAL CXCL1 and IFN-lambda levels were attenuated bv CRT in polyI:C challenged mice, the levels of these cytokines were not inhibited by CRT following influenza infection." (PMID 33381112, 2020).
glioblastoma (26 papers, 2014 to 2025). The most malignant astrocytic tumor (WHO grade IV). "Due to the important influence of CXCL1 on tumorigenic processes in glioblastoma tumors, elevated levels of this chemokine are associated with a worse prognosis for the patient." (PMID 38673949, 2024). "CXCL1 also causes the proliferation and self-renewal of cancer stem cells of glioblastoma." (PMID 38673949, 2024). "CXCL1 also causes cancer cell migration, as shown by experiments on glioblastoma cell lines." (PMID 38673949, 2024). "Glioblastoma cell-derived EVs upregulated the expression of the pro-tumor genes in microglia cells, including the CXCL1/10, CCL2/CCL5, and IL-6, and downregulated immune response-associated genes, such as IL-16, IL-23, and IL-2740." (PMID 39781357, 2025). "Studies on glioblastoma multiforme cells have shown that the increase in CXCL1 expression by ionizing radiation is casein kinase 1 alpha 1 (CK1α) dependent and dependent on an increase in inhibitor of NF-κBζ (IκBζ) expression." (PMID 40427171, 2025). "In glioblastoma multiforme, CXCL1 neutralizing antibody was shown to block MDSCs migration and resulted in an increase in CD8+ T cells in the tumor." (PMID 39394189, 2024). "Glioblastoma tumor cells secrete CXCL1, which results in the recruitment of mesenchymal stem cells into the tumor niche." (PMID 38673949, 2024). "A combination of CXCL1 neutralizing antibody and temozolomide chemotherapy was more effective than chemotherapy alone in treating glioblastoma multiforme, thereby extending OS." (PMID 39394189, 2024). "Depending on the literature cited, CXCL1 expression levels in glioblastoma tumors are either unchanged or elevated relative to healthy brain tissue." (PMID 38673949, 2024). "Cytokine profiling of the mesothelioma cell line suspension revealed significantly elevated production of G-CSF, GM-CSF, IL-8, CXCL1, and IL-1α compared to glioblastoma and acute myeloid leukemia cell lines." (PMID 39768223, 2024). "The increase in CXCL1 expression in glioblastoma cells following radiation therapy persists for up to 35 days." (PMID 38673949, 2024). "One available study shows that cerebrospinal fluid CXCL1 levels are elevated in patients with glioblastoma." (PMID 38673949, 2024). "CXCL1 also increases programmed death-ligand 1 (PD-L1) expression in glioblastoma cells, which enhances cancer immune evasion." (PMID 38673949, 2024). "CXCL1 overexpression induces the mesenchymal transition and imparts radiation resistance to glioblastoma cells by stimulating the NF-B signaling pathway in glioblastoma cells." (PMID 35897925, 2022). "Overall, our findings suggest that the elevation of CXCL1 indicates a poor prognosis and radioresistance by inducing mesenchymal transition in glioblastoma." (PMID 32187449, 2020). "One possible mechanism that can be targeted in glioblastoma tumors may be CXCL1 and its receptor CXCR2." (PMID 38673949, 2024). "Similarly, of silencing of CXCL1 attenuated the proliferation and radioresistance of glioblastoma cells." (PMID 35585513, 2022). "Also, CXCL1 expression is higher in recurrent glioblastoma than in primary glioblastoma." (PMID 38673949, 2024). "Also, high CXCL1 expression in glioblastoma tumors leads to an increase in the number of macrophages with M2 polarity, as well as granulocytic-myeloid-derived suppressor cells (G-MDSC) and monocytic-myeloid-derived suppressor cells (M-MDSC), which indicates an enhancement of cancer immune evasion." (PMID 38673949, 2024). "However, CXCL1 in glioblastoma tumors also has other pro-angiogenic properties." (PMID 38673949, 2024). "Moreover, a high level of CXCL1 was associated with radiosensitivity and poor prognosis in glioblastoma patients, and CXCL1 silence could reduce the proliferation and radioresistance of glioblastoma cells." (PMID 39394189, 2024).